ATP7B (ATPase copper transporting beta)
Diseases named in the same sentence as ATP7B in open-access papers (continued):
Sharing a sentence is not in itself a finding about the gene and the disease.
Cirrhosis (5 papers, 2015 to 2025). A chronic disorder of the liver in which liver tissue becomes scarred and is partially replaced by regenerative nodules and fibrotic tissue resulting in loss of liver function. "In line with our previous findings, hepatic Cu concentrations of Atp7b−/− mice at age 36 weeks were higher than those observed in control mice at age of 44 weeks, most likely indicating the ongoing tissue damage (cirrhosis) associated with intrahepatic Cu loss reported before." (PMID 34944677, 2021). "Experimental studies in mutant mice in which the copper-transporting ATPase gene (Atp7b) is disrupted revealed a drastic, time-dependent accumulation of hepatic copper that is accompanied by formation of regenerative nodes resembling cirrhosis." (PMID 25704483, 2015). "In a Atp7b−/− mouse model, miR-122-5p and miR-192-5p in serum mirrored the pattern observed in patients, while liver levels of both miRNAs decreased, especially at 40 weeks, coinciding with the progression from chronic hepatitis (30 weeks) to cirrhosis (36–44 weeks)." (PMID 39060521, 2024).
liver cancer (5 papers, 2022 to 2025). An epithelial or non-epithelial malignant neoplasm that arises from the liver. "In summary, EGCG induces the accumulation of copper in liver cancer cells by lowering the expression of ATP7B." (PMID 40136640, 2025). "In summary, we first report a new antitumor mechanism of EGCG, which disrupted intracellular copper homeostasis and facilitated cuproptosis in liver cancer cells by regulating the MTF1/ATP7B axis." (PMID 40136640, 2025). "Expression of the Cu transporter genes ATP7A, ATP7B, SLC31A1 and SLC31A2 were found significantly altered in liver cancer samples with elevated Cu levels." (PMID 37324184, 2023). "Cu transporter-related genes such as ATP7A, ATP7B, and SLC31A1 were singularly expressed or copied in liver cancer samples and a relative higher level of Cu was observed in HCC cell." (PMID 36438201, 2022). "The increase in copper content in liver cancer cell tissue is due to the loss of ATP7B, rather than SLC31A1 and SLC31A2 down-regulation; and in the liver, the lack of ATP7B affects its cell cycle and lipid metabolism." (PMID 38200525, 2024).
liver fibrosis (5 papers, 2015 to 2025). "The possible mechanisms involved are associated with reversing the ATP7B mutants, and exerting anti-oxidation, anti-inflammation and anti-hepatic fibrosis effects." (PMID 31001112, 2019). "The underlying mechanisms of CHM for WD are associated with reversing the ATP7B mutants, exerting anti-oxidation, anti-inflammation, and anti-hepatic fibrosis effects." (PMID 31001112, 2019). "Masson staining further demonstrated that liver fibrosis was significantly more pronounced in ATP7B−/− mice compared to controls." (PMID 41230834, 2025). "In our study, we observed a significant upregulation of Lox in the livers of ATP7B−/− mice, which suggests that copper accumulation in WD may drive hepatic fibrosis at least in part through the induction of LOX family members." (PMID 41230834, 2025).
lung carcinoma (5 papers, 2019 to 2026). "ATP7B is associated with a reduced risk of lung cancer and can serve as an indicator for predicting how patients will respond to platinum‐based chemotherapy." (PMID 40923717, 2026). "Researchers also found that the microsatellites of SLC31A1 and ATP7B were associated with lung cancer risk, suggesting that the expression levels of copper homeostasis-related genes may also influence the process of lung cancer development." (PMID 36882769, 2023). "ATP7B tag SNPs rs9535828 and rs9535826 were found to be correlated with platinum resistance in Chinese Han lung cancer patients." (PMID 36685880, 2022).
MEDNIK syndrome (5 papers, 2020 to 2024). "Disruptions in copper levels may affect ATP7B polarity, leading to abnormal copper metabolism and the manifestation of MEDNIK syndrome." (PMID 39000354, 2024).
depression (4 papers, 2021 to 2026). "Pineal night-specific ATPase (PINA) is a copper-dependent splice variant of ATP7B that may be involved in cirrhotic rhythms, sleep, and the pathogenesis of depression, especially in cases of impaired copper metabolism (as in patients with WD)." (PMID 39596417, 2024). "This is the first evidence that circSpna2 can ameliorate post‐TBI depression by attenuating cuproptosis through the circSpna2/Keap1/Nrf2/Atp7b signalling axis." (PMID 39581695, 2024). "Our study indicated that circSpna2 could regulate the expression of Atp7b to impact cuproptosis and alleviate depression status, also providing a new molecular therapy candidate for WD." (PMID 39581695, 2024). "Enhancing circSpna2 expression could mitigate depression after TBI by modulating the Keap1/Nrf2/Atp7b pathway." (PMID 39581695, 2024). "For instance, while altered copper metabolism (ATP7B) has been linked to depression, our results suggest it may not be a primary causal driver." (PMID 41601681, 2026).
prostate carcinoma (4 papers, 2016 to 2025). A carcinoma that arises from epithelial cells of the prostate gland. "The tx mutation in Atp7b hinders both of these functions, therefore we assessed whether it could influence prostate cancer growth in the TRAMP mouse model." (PMID 27175597, 2016). "For example, an increased Cu requirement by prostate cancer cells because the presence of a mutant Cu-transporting Atp7b protein may change Cu-integration in serum and cause a remarkable reduction in prostate cancer burden and disease severity, abrogating adenocarcinoma development." (PMID 36458167, 2022). "ATP7B may also serve as a therapeutic target to improve the efficacy of docetaxel in prostate cancer." (PMID 40316883, 2025). "In prostate cancer, elevated levels of CTR1, ATP7A, and ATP7B have been observed." (PMID 41516324, 2025).
bladder cancer (3 papers, 2016 to 2023). "We measured the mRNA expressions of MDR1, MRP1, MRP2, ABCG2, CTR1, ATP7A, and ATP7B in T24 and J82 bladder cancer cells in different groups." (PMID 27485374, 2016). "When bladder cancer cell lines RT4 and T24 were treated with large doses of cisplatin, both ATP7A and ATP7B expression levels were significantly reduced, while CTR1 gene activity remained unaltered." (PMID 36650399, 2023). "The roles of ABCC5, ABCA8, ABCC10, ABCB10, ABCG1, ATP7B, ABCG2, and mitochondrial SLC25A10 in platinum-receiving urinary bladder cancer patients should be the subject of further investigation." (PMID 36650399, 2023). "In the present study, we investigated the expressions of MDR1, MRP1, MRP2, CTR1, ATP7A, ATP7B, and ABCG2 in T24 and J82 bladder cancer cells treated with emodin and cisplatin alone or in combination." (PMID 27485374, 2016). "Additionally, studies on the potential role of ATP7B in colorectal and ovarian cancer have confirmed that its overexpression is tied to a poor response to platinum treatment, but not in urinary bladder cancer patients, calling for further needed research to be conducted." (PMID 36650399, 2023).
diabetes (3 papers, 2014 to 2024). "Further investigation of the deep links between ATP7A/ATP7B and diabetes should be conducted to provide a deeper understanding of the development of this condition." (PMID 38904034, 2024). "The decreased localization of ATP7B to the sarcolemmal membrane and intercalated disc regions in diabetes could limit intercellular transport of copper." (PMID 24927960, 2014). "To date, only the ATP7A protein is markedly downregulated in vessels isolated from T2DM patients and diabetic mice, whereas how the other copper transporters, ATP7B and SLC31A1, change in diabetes was uncertain." (PMID 36675183, 2023). "Furthermore, diabetes depressed levels of additional intracellular copper-transporting proteins, including antioxidant-protein-1 (ATOX1) and copper-transporting-ATPase-2 (ATP7B), whereas TETA elevated copper-transporting-ATPase-1 (ATP7A)." (PMID 24927960, 2014).
Hepatitis (3 papers, 2021 to 2025). Inflammation of the liver. "As Atp7b−/− rats shortly die upon hepatitis onset, we thus switched to cellular studies here to investigate potential toxicity to such copper pulses, that is, loosely albumin-bound copper." (PMID 34857647, 2022).
iron deficiency (3 papers, 2016 to 2020). "In cultured human skin fibroblasts, small and inconsistent effects of adding Cu (concentrations unknown) or Cu chelators on mRNA expression were observed for ATP7B, but there was a more clear-cut positive effect when adding the Fe(II)-chelator, ferrozine, to cause iron deficiency." (PMID 32668621, 2020). "However, they noticed that hepatic Atp7b gene expression was not altered during iron deficiency." (PMID 33396831, 2020).
psoriasis (3 papers, 2023 to 2025). An autoimmune condition characterized by red, well-delineated plaques with silvery scales that are usually on the extensor surfaces and scalp. "We established a genetic model for predicting psoriasis susceptibility based on three candidate cuproptosis-related genes (CRGs), MTF1, ATP7B, and SLC31A1, and found that patients can gain clinical benefits based on this model." (PMID 37091865, 2023). "To explore the correlation between key cuproptosis genes and drug sensitivity in psoriasis, we analyzed the sensitivity between ATP7B, SLC31A1, and MTF1 expression and drug sensitivity using the “pRRophetic” R package." (PMID 37091865, 2023). "Notably, transcriptomic analyses have revealed the significant upregulation of cuproptosis-associated genes (MTF1, ATP7B, and SLC31A1) in psoriatic patients, while additional clinical research has demonstrated elevated serum copper levels in individuals with psoriasis." (PMID 40332377, 2025). "Then, through establishing an RF model, we used the three candidate genes as cuproptosis regulators (MTF1, ATP7B, and SLC31A1) to predict the occurrence of psoriasis." (PMID 37091865, 2023). "We observed the expression of cuproptosis-related proteins, including ATP7B, SLC31A1, and MTF1, in psoriasis." (PMID 37091865, 2023). "Co-expression of ATP7B, SLC31A1, and MTF1 suggests that these key cuproptosis genes may jointly influence psoriasis development." (PMID 37091865, 2023). "The ROC curve prediction of the explored model genes (MTF1, ATP7B, and SLC31A1) showed that they could be used to reasonably predict the presence of psoriasis." (PMID 37091865, 2023). "The accumulation of intracellular copper leads to cell death, and the cuproptosis-related genes MTF1, ATP7B, and SLC31A1 are increasingly expressed in patients with psoriasis compared to patients without psoriasis." (PMID 38256115, 2024).
steatosis (3 papers, 2021 to 2024). Increased lipid within the cytoplasm of cells. "The genetic loss of function in ATP7B results in copper accumulation, primarily affecting the liver and manifesting with hepatocellular steatosis, necro inflammation, and fibrosis." (PMID 38072238, 2024). "In this regard, Atp7b−/−-B6 mice were again similar to Atp7b−/− hybrid animals, which had a pronounced inflammatory response and no significant steatosis." (PMID 33707579, 2021). "Both tx-j and Atp7b−/− B6 had no micro/macrovascular steatosis or signs of fibrosis." (PMID 38072238, 2024).
brain cancer (2 papers, 2022). A primary or metastatic malignant neoplasm affecting the brain. "Brain cancers (GBM and LGG) were found to potentially have a higher copper metabolism-related cell death compared to normal brain tissue because their anti-cuproptosis gene ATP7B was downregulated with pro-cuproptosis genes SLC31A1, FDX1, DLAT, and LIAS upregulated in cancer tissues." (PMID 36276096, 2022).
cervical cancer (2 papers, 2020 to 2024). A primary or metastatic malignant neoplasm involving the cervix. "We demonstrated that triptolide upregulated COMMD1 expression and downregulated ATP7A and ATP7B expression by inhibiting XIAP, thereby promoting intracellular copper accumulation and subsequently inducing cuproptosis in cervical cancer cells." (PMID 39198750, 2024). "However, when the cells were treated with PTX, this drug induced the downregulation of the ATP7A, ATP7B, CTR1, MRP-2, and GSR genes in both cervical cancer cell lines." (PMID 33680921, 2020).
cognitive decline (2 papers, 2021 to 2023). "In addition, copper treatment increased NLRP3 expression, and NLRP3 knockdown mitigate neurodegeneration and cognitive decline in ATP7B knockout mice." (PMID 37928399, 2023).
deafness (2 papers, 2023). An inherited or acquired condition characterized by the complete loss of the ability to hear from one or both ears. "After genetic counseling, her spouse chose to undergo sequencing for the target genes (GJB2 and ATP7B), namely, GJB2: c.109G > A (p.Val37Ile), was detected, which usually leads to autosomal recessive hereditary deafness." (PMID 37031186, 2023).
dementia (2 papers, 2021 to 2024). Loss of intellectual abilities interfering with an individual's social and occupational functions. "These considerations are suggestive of the fact that carriers of WD ATP7B heterozygosity or carriers of AD related ATP7B SNPs might be sensitive to Cu exposure and be at risk for developing dementia." (PMID 34209820, 2021).
Dysarthria (2 papers, 2022). Dysarthric speech is a general description referring to a neurological speech disorder characterized by poor articulation. "In ATP7B heterozygous mutation carriers dysarthria has been reported." (PMID 36553628, 2022). "Since the ATP7B protein is also expressed in different regions of the brain, the properties of various ATP7B variants may play a role in the occurrence of dysarthria." (PMID 35220961, 2022).
gastric cancer (2 papers, 2023 to 2024). A primary or metastatic malignant neoplasm involving the stomach. "Copper ions are mainly involved in gastric cancer cell resistance through changes in copper homeostasis after binding to copper transporter ATP7B and cisplatin, leading to increased resistance to cisplatin." (PMID 38370477, 2024). "Regarding the resistance of cancer cells, including gastric cancer cells, to platinum-based chemotherapy, ongoing research suggests that the interaction between the copper ion transporter ATP7B and cisplatin disrupts copper homeostasis, thereby augmenting resistance to platinum-based drugs." (PMID 38370477, 2024).
haemochromatosis (2 papers, 2025). "The c.845G>A (p.Cys282Tyr) variant in the HFE gene, responsible for hereditary hemochromatosis, was the most common (4 carriers), while the c.2304dup (p.Met769Hisfs*26) variant in the ATP7B gene was identified in one individual." (PMID 40699671, 2025).
Hearing impairment (2 papers, 2024). A decreased magnitude of the sensory perception of sound. "Overall, we propose a new candidate gene, ATP7B, for congenital hearing loss and novel variants in known HL genes, which expands our understanding of the etiology of HL." (PMID 39767564, 2024).
lipid metabolism disorders (2 papers, 2024 to 2025). "It is also necessary to continue to explore the pathogenesis of copper and copper transporters, such as copper- transporting p-type adenosine triphosphatase 1 (ATP7A) and 2 (ATP7B), in lipid metabolism disorders." (PMID 37132140, 2024). "Some studies have also found that ATP7B can impact lipid metabolism disorders." (PMID 41462995, 2025).
lymph node metastasis (2 papers, 2024 to 2025). "Multivariate analysis of DFS revealed ‘lymph node metastasis’ (HR, 3.56; 95% CI 1.42–8.92; p = 0.007) and ‘low ATP7B expression’ (HR, 2.82; 95% CI 1.15–6.92; p = 0.024) as independent prognostic factors." (PMID 40316883, 2025). "Multivariate analysis of OS revealed ‘lymph node metastasis’ (HR, 4.71; 95% CI 1.75–12.7; p = 0.002), ‘ER negative’ (HR, 7.92; 95% CI 1.01–61.8; p = 0.048), and ‘low ATP7B expression’ (HR, 2.38; 95% CI 1.02–5.57; p = 0.046) as independent prognostic factors." (PMID 40316883, 2025). "The ATP7B C/N ratios were not predominant in the T category, lymph node metastasis, or UICC stage." (PMID 40316883, 2025).
renal clear cell adenocarcinoma (2 papers, 2022 to 2025). "The results demonstrated that ATP7B, DLAT, and LIAS were upregulated in the 786-O cell line, which represented human renal clear cell adenocarcinoma cell, compared to the HK-2 cell line; while DBT and PDHB were found to be downregulated in 786-O cells." (PMID 36092880, 2022).
acute liver failure (1 paper, 2023). Rapid deterioration of liver function causing encephalopathy and coagulopathy. "We report a unique case presenting with solitary organ involvement as acute liver failure with novel ATP7B gene mutation, which has never been reported before." (PMID 36777461, 2023).
autoimmune thyroid disease (1 paper, 2024). Inflammatory disease of the thyroid gland due to autoimmune responses leading to lymphocytic infiltration of the gland. "Furthermore, we found that ATP7B was associated with antigen processing and presentation, autoimmune thyroid disease, type I diabetes mellitus and intestinal immune network for IgA production, while NFE2L2 was involved in the Toll-like receptor signaling pathway." (PMID 38690269, 2024).
Becker muscular dystrophy (1 paper, 2025). Becker muscular dystrophy (BMD) is a neuromuscular disease characterized by progressive muscle wasting and weakness due to degeneration of skeletal, smooth and cardiac muscle. "In 5 couples, both partners have P/LP variants in the same AR gene (CFTR, GJB2, ATP7B, DHCR7), and in one couple, a woman has a clinically significant variant in the DMD gene linked to Becker muscular dystrophy." (PMID 41595422, 2025).
Breast invasive carcinoma (1 paper, 2020). "Survival analyses of ATP7A and ATP7B were used to evaluate their effects on the development of Breast invasive carcinoma (BRCA)." (PMID 32508020, 2020).
breast tumors (1 paper, 2022). "Among them, the expression of the majority of genes was decreased in tumor samples except for four genes (ATP7B, SLC31A1, PDHB and CDKN2A), suggesting cuproptosis signaling was significantly downregulated in breast tumors." (PMID 36497253, 2022).
cholangiocarcinoma (1 paper, 2025). A carcinoma that arises from the intrahepatic biliary tree (intrahepatic cholangiocarcinoma) or from the junction, or adjacent to the junction, of the right and left hepatic ducts (hilar cholangiocarcinoma). "In agreement with this, we observed the highest expression of PrP in cholangiocarcinoma nodes in the liver of Atp7b−/− mice, whereas PrP depletion almost completely prevented tumor growth." (PMID 39922819, 2025).
cholestasis (1 paper, 2026). Impairment of the bile flow caused by obstruction within the liver, or outside the liver in the bile duct system. "These expandable G-heporgs demonstrated regenerative competence and faithfully recapitulated hepatocyte polarity and functional bile canalicular networks, as evidenced by ATP7B copper-dependent translocation and drug-induced cholestasis assays." (PMID 41888105, 2026).
distal myopathy (1 paper, 2024). Distal myopathy refers to a group of muscle diseases which share the clinical pattern of predominant weakness and atrophy beginning in the feet and/or hands. "Notably, in individual ITA04, two LP variants (ATP7B: c.1993A>G and COL6A2: c.1572+1G>A) were reported; we observed that these variants co-segregated in their relatives diagnosed with SFN and distal myopathy." (PMID 39000354, 2024).
dyslipidemia (1 paper, 2024). "Based on a review of the literature, it is hypothesized that dyslipidemia in WD patients may be linked to copper overload and its effects on lipid metabolism-related pathways, as well as the modulation of intestinal lipid metabolism by ATP7B." (PMID 39634771, 2024).
endometrial carcinoma (1 paper, 2022). A malignant tumor arising from the epithelium that lines the cavity of the uterine body. "Overexpression of ATP7B in endometrial carcinoma was correlated with poor outcomes in patients treated with cisplatin-based chemotherapy." (PMID 36567939, 2022).